MTREX (Mtr4 exosome RNA helicase)
Description:
Catalyzes the ATP-dependent unwinding of RNA duplexes with a single-stranded 3' RNA extension. Central subunit of many protein complexes, namely TRAMP-like, nuclear exosome targeting (NEXT) and poly(A) tail exosome targeting (PAXT). NEXT functions as an RNA exosome cofactor that directs a subset of non-coding short-lived RNAs for exosomal degradation. NEXT is involved in surveillance and turnover of aberrant transcripts and non-coding RNAs. PAXT directs a subset of long and polyadenylated poly(A) RNAs for exosomal degradation. The RNA exosome is fundamental for the degradation of RNA in eukaryotic nuclei. Substrate targeting is facilitated by its cofactor ZCCHC8, which links to RNA-binding protein adapters. Associated with the RNA exosome complex and involved in the 3'-processing of the 7S pre-RNA to the mature 5.8S rRNA. May be involved in pre-mRNA splicing. In the context of NEXT complex can also in vitro unwind DNA:RNA heteroduplexes with a 3' poly (A) RNA tracking strand. Can promote unwinding and degradation of structured RNA substrates when associated with the nuclear exosome and its cofactors. Can displace a DNA strand while translocating on RNA to ultimately degrade the RNA within a DNA/RNA heteroduplex. Plays a role in DNA damage response.
Synonyms: DOB1; KIAA0052; MTR4; SKIV2L2; fSAP118
Tractability: Small molecule: a structure with a bound ligand is known. PROTAC: UniProt records ubiquitination sites on it; ubiquitination databases record sites on it; a small molecule that binds it is known.
Target class: Enzyme; Hydrolase
Gene: Protein-coding gene on chromosome 5 (55,307,736 to 55,426,065, forward strand). Ensembl gene ENSG00000039123.
Subcellular location: Nucleus, nucleoplasm; Nucleus, nucleolus; Nucleus; Nucleus speckle
Subcellular location (Human Protein Atlas): Nucleoplasm
Pathways (Reactome):
Metabolism of RNA: Major pathway of rRNA processing in the nucleolus and cytosol; Nuclear RNA decay; mRNA Splicing - Major Pathway
Gene expression (Transcription): Regulation of endogenous retroelements by the Human Silencing Hub (HUSH) complex
Gene Ontology:
Molecular function: ATP binding; ATP hydrolysis activity; protein binding; RNA binding; RNA helicase activity; nucleic acid binding
Biological process: DNA damage response; maturation of 5.8S rRNA; RNA catabolic process; rRNA processing; mRNA splicing, via spliceosome; snRNA catabolic process; mRNA metabolic process
Cellular component: catalytic step 2 spliceosome; exosome (RNase complex); nuclear exosome (RNase complex); nuclear exosome targeting complex; nuclear speck; nucleoplasm; nucleus; TRAMP complex; nucleolus
Genetic constraint (gnomAD): Loss-of-function variants: 24 observed, 52.21 expected, observed/expected ratio (o/e) 0.46, 90% interval 0.33 to 0.65. The upper end of that interval is the gene's LOEUF score, 0.65, which puts it in group 2 of 6, group 1 being the genes least tolerant of losing a copy. Missense variants: 512 observed, 664.25 expected, observed/expected ratio (o/e) 0.77, 90% interval 0.72 to 0.83. Synonymous variants: 218 observed, 219.16 expected, observed/expected ratio (o/e) 0.99, 90% interval 0.89 to 1.11.
Homologues: Orthologues: chimpanzee MTREX (99% identical), rabbit MTREX (99% identical), dog MTREX (99% identical), pig MTREX (99% identical), guinea pig MTREX (98% identical), macaque MTREX (98% identical), mouse Mtrex (98% identical), rat Mtrex (97% identical), tropical clawed frog mtrex (86% identical), zebrafish mtrex (85% identical), Drosophila melanogaster Mtr4 (62% identical), Caenorhabditis elegans mtr-4 (50% identical). Paralogues in human: SKIC2 (36% identical), POLQ (21% identical), ASCC3 (15% identical), DDX60L (15% identical), DDX60 (14% identical), HELQ (14% identical), SNRNP200 (14% identical), HFM1 (13% identical).
Diseases named in the same sentence as MTREX in open-access papers:
MTREX is named in the same sentence as 11 diseases in open-access papers, as found by Europe PMC text mining. Sharing a sentence is not in itself a finding about the gene and the disease. The quoted sentences say what the papers report.
infection (5 papers, 2018 to 2025). The state of being infected such as from the introduction of a foreign agent such as serum, vaccine, antigenic substance or organism. "In patients with poor outcome and infection, PSME1, MTREX, and H2B1C were more abundant in T cell-derived EVs; COHA1 was less abundant in B cell-derived EVs; and PCSK9 and CMC1 were less abundant in the monocyte-derived EVs." (PMID 41345658, 2025).
tumor (4 papers, 2019 to 2023). "The correct splicing of GLUT1 and PKM2 in HCC was found to be regulated by an RNA helicase, MTR4 (also known as MTREX), which, when depleted, decreased tumour growth in vivo." (PMID 35014671, 2022).
MTREX also shares sentences with these, for which no sentence is quoted: cancer (4 papers); hepatocellular carcinoma (1); HIV-1 infection (1); leukemia (1); lymphoma (1); multiple myeloma (1); oral cancer (1); ovarian carcinoma (1); virus infection (1).